PGAM1 (phosphoglycerate mutase 1)
Diseases named in the same sentence as PGAM1 in open-access papers (continued):
Sharing a sentence is not in itself a finding about the gene and the disease.
tumor (continued). "PKM2 also catalyzes phosphorylation of phosphoglycerate mutase 1 (PGAM1) at histidine 11, which enhances aerobic glycolysis and promotes tumor growth." (PMID 40842995, 2025). "Phosphoglycerate mutase 1 (PGAM1), a key glycolytic enzyme, has been implicated in tumor progression and metastasis, and its expression is up-regulated in patients with BC." (PMID 40548063, 2025). "This study identifies that SEC61G drives glycolytic metabolism by stabilizing PGAM1, a process that not only provides sufficient energy for tumor cells but also alters the tumor microenvironment through lactate secretion." (PMID 39990664, 2025). "PGAM1 promotes the accumulation of glycolytic intermediates, providing energy and biosynthetic precursors for rapid tumor growth." (PMID 39990664, 2025). "Analysis of HCC patients treated with immunotherapy, who demonstrated an enlargement of tumor size, had higher PGAM1 expression as well as lower CD8 expression." (PMID 41339932, 2025). "PGAM1 facilitates the conversion of glycolytic intermediates, providing energy and biosynthetic precursors for rapid tumor cell growth and proliferation." (PMID 39990664, 2025). "PGAM1 inhibition synergizes with anti-PD-1 immunotherapy significantly remodeling the tumor microenvironment and leading to an increase in antitumor immunocytes and a reduction in immunosuppressive cell infiltration." (PMID 40046063, 2025). "SMC4 also regulates PGAM1 transcription, and dual loss of SMC4 and PGAM1 disrupts F‐actin assembly, causing cell division failure and polyploidy, ultimately suppressing tumour proliferation." (PMID 41020792, 2025). "In summary, SEC61G drives an immunosuppressive, tumor-promoting microenvironment in brain metastases through the PGAM1-mediated glycolytic pathway, offering a potential therapeutic target to enhance anti-tumor immunity." (PMID 39990664, 2025). "PGAM1 expression is positively correlated with infiltration levels of tumor-promoting immune cells such as macrophages, NK cells, and myeloid dendritic cells." (PMID 40046063, 2025). "PGAM1, as a central enzyme in the glycolytic pathway, plays a key role in tumor metabolic reprogramming." (PMID 39990664, 2025). "The level of PGAM1 pY119 phosphorylation in tumor cells or tissues is significantly higher than that of untransformed cells or tumor-adjacent tissues; accordingly, PGAM1 H11 phosphorylation was co-related Y119 phosphorylation." (PMID 38750259, 2024). "All tumor types were selected from the TCGA dataset and the correlation coefficients of PGAM1 expression with TMB and MSI were calculated." (PMID 38434965, 2024). "Due to the well-characterized link between PEP and PGAM1 H11 phosphorylation in tumor cells, PEP-consuming metabolic enzymes emerge into our consideration." (PMID 38750259, 2024). "In this study, we tried to investigate the relationship between PGAM1 and tumor immune status and analyzed the expression correlation between PGAM1 and 23 immune checkpoint molecules by using the TCGA database." (PMID 38434965, 2024). "PKM2 phosphorylates PGAM1 at H11 and this unique posttranslational modification elevates the enzymatic activity of the latter, thereby enhances glycolysis shunts and promotes tumor growth." (PMID 38750259, 2024). "The differences in the phosphorylation levels of PGAM1 in normal and primary tumor tissues were further explored." (PMID 38434965, 2024). "Collectively, these results suggest that PGAM1 pY119 phosphorylation regulated by PKM2 specify the tumor tissues from the normal counterparts and signify an unfavorable prognosis." (PMID 38750259, 2024). "Y119 phosphorylation, PKM2 binding, H11 phosphorylation and the enzymatic activity of PGAM1 from the tumor xenografts were further examined, and they were all significantly declined due to pY119-TAT peptide injection." (PMID 38750259, 2024).
tumor (continued). "Based on this specificity of Y119 phosphorylation in tumor cells, a cell-permeable peptide, which was derived from PGAM1 and contained phosphorylated Y119, was designed and fused with HIV-TAT (pY119-TAT)." (PMID 38750259, 2024). "In this work, through unveiling the glycolytic enzyme PKM2-mediated PGAM1 H11 phosphorylation, we identify a unique histidine kinase in tumor cells that exploits PEP as phosphodonor." (PMID 38750259, 2024). "The results showed that PGAM1 was differentially expressed in most tumor tissues, with upregulation in most tumors while downregulation in a few." (PMID 38434965, 2024). "First, we systematically analyzed the expression patterns of PGAM1 in different tumor types using PGAM1 mRNA expression profile microarray data from 33 solid tumors in the TCGA-GTEx and TCGA databases." (PMID 38434965, 2024). "The enhancing effect of circDDX21 on xenograft tumor growth was completely diminished by PGAM1 knockdown." (PMID 38773094, 2024). "In tumor-bearing mice, AS-IV treatment suppressed the tumor growth and the succinylation of PGAM1, while KAT2A overexpression reversed these results." (PMID 38835015, 2024). "Increasing evidence of recent studies revealed that the level of phosphoenolpyruvate (PEP), a metabolite downstream of PGAM1 and generated from 2PG in glycolysis, is significantly upregulated in tumor cells as compared to that from adjacent normal tissues." (PMID 38750259, 2024). "In this paper, we systematically analyzed the relationship between PGAM1 expression and tumor infiltration of various immune cells." (PMID 38434965, 2024). "In tumor-bearing mice, AS-IV suppressed tumor growth though inhibiting KAT2A-mediated succinylation of PGAM1." (PMID 38835015, 2024). "PGAM1 plays an important role in coordinating glycolysis with its shunts and is crucial for tumor cell proliferation; however, the comprehension of the functional regulation of this key metabolic enzyme still remains elusive." (PMID 38750259, 2024). "We identified that genetic knockdown of Pgam1 significantly decreased tumor growth in C57BL/6 mice (immunocompetent) compared with that in nude (immunodeficient) mice." (PMID 37705495, 2023). "Present studies on PGAM1 have mainly focused on the metabolic regulation of metabolism and molecular signaling pathways inside tumor cells." (PMID 37705495, 2023). "The results revealed a significant inhibition in tumor growth and a decrease in tumor volume and weight in mice in PGAM1 knockdown group compared to the control group." (PMID 37542027, 2023). "Meanwhile, it was demonstrated that the phosphorylation of tyrosine 26 residue of PGAM1 greatly enhances its activity by enhancing the binding of PGAM1 to its substrates, and thus upregulates glycolysis and promotes tumor growth." (PMID 36732657, 2023). "Elevated expression of PGAM1 is often correlated with aggressive tumor phenotypes, poor prognosis, and reduced patient survival rates." (PMID 37338518, 2023). "Based on matched tumor and normal tissues from the patients in Human Protein Atlas, we found both PGAM1 and ENO1 were up-regulation in tumor side." (PMID 37065499, 2023). "In the retrospective analysis of the metabolome profiling data from tumour tissues, levels of 2‐PG, phosphoenolpyruvate and pyruvate, which were downstream products of PGAM1, were observed to decrease in the RFX6‐KO group and increase in the RFX6‐OE group." (PMID 38093528, 2023). "Subcutaneous models revealed that silencing PGAM1 suppressed the RFX6‐induced cell proliferation in vivo, presenting as attenuated tumour volumes, tumour weights and Ki67+ cells in the stable PGAM1‐KD groups." (PMID 38093528, 2023). "Intriguingly, in previous reports researchers have specifically identified PGAM1 as a pro-oncogenic protein that is upregulated in BC cells, supporting aerobic glycolysis and tumor cell growth." (PMID 36599909, 2023).
tumor (continued). "To investigate the immune relevance of PGAM1, we targeted Pgam1 (both genetically and pharmacologically) to observe tumor growth and tumor weight in a xenograft experiment in which C57BL/6 mice were subcutaneously injected with Hepa16 cells." (PMID 37705495, 2023). "IHC staining of tumour tissues from previous models also showed the decreased expression of PGAM1 in the RFX6‐KO cells and increased expression in the RFX6‐OE cells in vivo, supporting the transcriptional regulation of PGAM1 by RFX6 in HCC cells." (PMID 38093528, 2023). "The present study investigates the clinical relevance of glycolytic factors, specifically PGAM1, in the tumor microenvironment of kidney renal clear cell carcinoma (KIRC)." (PMID 37847178, 2023). "Consistently, we confirmed here that elevated expression of PGAM1 was related to worse prognosis in publicly available datasets and tumor samples of BC." (PMID 35674458, 2022). "PGAM1 promotes tumor progression and aggravates tumor cells via activated glycolysis and interaction with SMA." (PMID 36077431, 2022). "It is imperative to dissect the molecular mechanisms of PGAM1 in tumorigenesis to enable the development of new PGAM1 inhibitors for tumor combination therapy." (PMID 35674458, 2022). "In vivo experiments further validated that PGAM1 promoted tumor growth in BC by altering ASS1 expression." (PMID 35674458, 2022). "Phosphoglycerate mutase 1 (PGAM1) is a critical glycolytic enzyme involved in tumor progression and metastasis." (PMID 35674458, 2022). "HKB99 is also active against EGFR-specific low molecular erlotinib-resistant tumor cells, emphasizing the importance of PGAM1 inhibitors such as HKB99 for a tumor-therapeutic agent." (PMID 36077431, 2022). "Another research in BC showed that PGAM1 directly binds to α‐smooth muscle actin gene to mediate the assembly, movement, and metastatic potential of tumor cells in a metabolically independent manner." (PMID 35674458, 2022). "In this study, we revealed a new mechanism whereby the tumor cells regain the expression of ASS1 by the knockdown of PGAM1." (PMID 35674458, 2022). "Phosphoglycerate mutase 1 (PGAM1) is an important enzyme in the glycolysis pathway and is related to tumor cell metastasis." (PMID 35840984, 2022). "A recent study documented that PGAM1 is activated by miR‐3614‐5p and serves a pro‐tumor role in tumor progression via regulation of transforming growth factor‐β signaling in NSCLC." (PMID 35674458, 2022). "Collectively, these data suggest that the molecular network mediated by PGAM1 is complex and essential for tumor development." (PMID 35674458, 2022). "Blocking of PGAM1 suppresses mTOR-mediated tumor growth, and PGAM1 abundance is an unfavorable predictor in patient survival." (PMID 35810157, 2022). "For example, an allosteric inhibitory agent, HKB99, immobilizes the PGAM1 confirmation to suppress growth and metastasis of tumor cells." (PMID 36077431, 2022). "We demonstrated that the restoration of PGAM1 expression rescued the sja-miR-61-mediated anti-tumor effects." (PMID 34221971, 2021). "Phosphoglycerate mutase (PGAM1) is a glycolytic enzyme that is involved in glycolysis and metabolic activity in tumor growth, survival, and invasion." (PMID 33668689, 2021). "Compared to oxaliplatin-treated mice, combination of C. tropicalis up-regulated the mRNA expression of pivotal glycolysis-related enzymes in tumor tissues, including Pgam1, Pkm2, Ldha and Pfkfb3." (PMID 34345205, 2021). "Recent studies have proven that once the expression of PGAM1 is upregulated, it will promote tumor cell proliferation and tumor growth in coordination with glycolysis and biosynthesis." (PMID 34899321, 2021).
tumor (continued). "We found 5 potential target genes (SKP2, SMO, SDCBP, FERMT2 and PGAM1) that were consistently predicted by the three softwares and involved in tumor-related signaling pathway." (PMID 34221971, 2021). "Downregulation of the expression of PGAM1 or suppression of its metabolic activity will lead to weakened cell proliferation and tumor growth." (PMID 34899321, 2021). "Consistently, our functional experiments revealed that the tumor inhibition effect of miR-3614-5p is in part mediated by the downregulation of PGAM1 in vitro and in vivo." (PMID 32855383, 2020). "After 5 weeks, we observed that the mice injected with PGAM1- knockdown A549 cells had reduced tumor weight and volume compared with those in mice injected with control cells." (PMID 32855383, 2020). "Xenograft tumor experiment in nude mice also showed that circ‐PGAM1 silencing combined with miR‐542‐3p overexpression resulted in the smallest tumor volume, indicating that circ‐PGAM1 exerted tumor‐promotion function through the downregulation of miR‐542‐3p." (PMID 32167655, 2020). "Compared to circ‐PGAM1(−)‐NC + pre‐NC group, the tumor volumes significantly decreased in circ‐PGAM1(−) group, pre‐miR‐542‐3p group, and circ‐PGAM1(−) + pre‐miR‐542‐3p group." (PMID 32167655, 2020). "The findings from current study demonstrate that PGAM1 plays critical roles in mTOR-mediated Warburg effect and tumor growth." (PMID 29362480, 2018). "Reduction of PGAM1 significantly attenuated the tumor formation of Pten−/− MEFs in nude mice and prolonged the survival of these tumor bearing mice." (PMID 29362480, 2018). "In this study, we first investigated mTOR regulation of PGAM1 expression and then the role of PGAM1 in mTOR-mediated glycolysis and tumor growth." (PMID 29362480, 2018). "As a downstream effector of mTOR, PGAM1 is critical for oncogenic mTOR-mediated cell proliferation and tumor formation." (PMID 29362480, 2018). "Accordingly, downregulation of PGAM1 expression or inhibition of its metabolic activity leads to attenuated cell proliferation and tumor growth." (PMID 28611670, 2017). "PGAM1 and ENO1 repression produce a decrease in the glycolytic flux associated with a reduction of tumor growth." (PMID 26918450, 2016). "Although the tumors of all mice were approximately equal in initial volumes, significant differences in tumor growth were observed upon treatment with PGAM1-shRNA-a." (PMID 20403181, 2010). "In comparison, tumor volumes in mice treated with PGAM1-shRNA-a were 212.71 ± 24.28 mm3, which were on average over 58.7% smaller than those in controls treated with PBS (Student's t test, p < 0.01)." (PMID 20403181, 2010). "SEC61G inhibitors could destabilize PGAM1, while PGAM1 inhibitors could block its enzymatic activity, jointly suppressing tumor metabolism and improving the immunosuppressive tumor microenvironment." (PMID 39990664, 2025). "PGAM1 correlates with aggressive tumor features (high grade, TNM stage)." (PMID 40977684, 2025). "This study aims to systematically investigate the biological functions of SEC61G in NSCLC brain metastases, with a particular focus on its potential regulation of PGAM1 activity and metabolic reprogramming, as well as its impact on the tumor immune microenvironment." (PMID 39990664, 2025). "Supporting this hypothesis, protein-protein interaction networks and epigenetic regulatory analyses revealed that SEC61G, PGAM1, and UBE3C are closely linked in processes such as protein ubiquitination and tumor metabolic regulation." (PMID 39990664, 2025). "Furthermore, PGAM1-mediated metabolic reprogramming can influence the tumor microenvironment, such as through lactate secretion, which modulates immune cell function and enhances immune evasion." (PMID 39990664, 2025). "Of particular interest is the possibility that SEC61G and PGAM1 may function coordinately to regulate tumor metabolism and the immune microenvironment during brain metastasis." (PMID 39990664, 2025).
tumor (continued). "In summary, this study not only demonstrates PKM2 function as a histidine kinase to phosphorylate PGAM1 to coordinate the glycolysis with its shunts during the rapid proliferation of the tumor cells, but also illustrates an enzyme-crosstalk-based regulatory mode during metabolic reprogramming." (PMID 38750259, 2024). "Taken together, AS-IV suppressed tumor growth via inhibiting KAT2A-mediated succinylation of PGAM1." (PMID 38835015, 2024). "Previous studies have shown high expression of PGAM1 in multiple tumor types." (PMID 38434965, 2024). "And we found that PGAM1 positively regulated TAMs tumor infiltration, suggesting that there may be positive feedback between them." (PMID 38434965, 2024). "Together, these results support the hypothesis that PGAM1 may intervene in the tumor immune microenvironment and tumor formation by regulating the functional status of multiple immune cells." (PMID 38434965, 2024). "PGAM1 was found to promote tumor growth through the coordination of glycolysis and biosynthesis." (PMID 38542116, 2024). "Evidently, PGAM1 Y119 phosphorylation constitutes the discrepancy between tumor cells and the normal proliferating ones, which is appealing an interpretation of the signaling mechanism that exists in tumor cells." (PMID 38750259, 2024). "In addition, our analysis of 23 pairs of matched tumor and non-tumor tissues from TCGA revealed that PGAM1 is typically overexpressed in the tumor tissues." (PMID 38434965, 2024). "In summary, PGAM1 may affect tumor infiltration of TAMs and NK cells and other cells, up-regulate PD-L1 and ultimately achieve inhibition of CTLs and NK cells immune cytotoxic clearance function." (PMID 38434965, 2024). "Besides, the expression of PGAM1 protein in normal and tumor tissues from various organs was investigated by using the Human Protein Atlas (HPA) database." (PMID 38434965, 2024). "A PGAM1-derived pY119-containing cell-permeable peptide or Y119 mutation disrupts the interaction of PGAM1 with PKM2 and PGAM1 H11 phosphorylation, dampening the glycolysis shunts and tumor growth." (PMID 38750259, 2024). "In addition, PGAM1 regulates apoptosis, epithelial mesenchymal transformation, and tumor immune microenvironment by up-regulating effector molecules such as Bcl2, Snail, and PD-L1." (PMID 38434965, 2024). "We also found that PGAM1 expression is affected by epigenetic mechanisms and may be an important regulator of tumor metabolism." (PMID 38434965, 2024). "We also found that patients with high PGAM1 mRNA expression were often accompanied by elevated tumor grading status, suggesting that PGAM1 may be involved in regulating tumor progression." (PMID 38434965, 2024). "However, the in-depth mechanism of PGAM1 from molecular phenotype to tumor formation, and the safety and efficacy evaluation of PGAM1-targeted therapy strategy still need to be further verified by experimental techniques." (PMID 38434965, 2024). "The overexpression of PGAM1 in UVM tumor tissues was verified by immunohistochemistry." (PMID 38434965, 2024). "Importantly, inhibition of the expression or activation of PGAM1 by shRNA or small molecule inhibitors suppresses glycolysis and anabolic biosynthesis, and reduces cell proliferation as well as tumor growth." (PMID 38750259, 2024). "CircDDX21 knockdown-reduced xenograft tumor growth was markedly recovered by PGAM1 overexpression." (PMID 38773094, 2024). "The TNM staging results indicated that PGAM1 was upregulated in high-stage tumor tissues." (PMID 38434965, 2024). "Pgam1 activity upregulates various tumor growths by promoting cell proliferation." (PMID 38773312, 2024). "In addition, the same trend was observed in the other four glycolysis enzyme markers, and we validate ENO1 and PGAM1 were overexpression in matched tumor part compared to normal side." (PMID 37065499, 2023).